CDH1 (cadherin 1)
Diseases named in the same sentence as CDH1 in open-access papers (continued):
Sharing a sentence is not in itself a finding about the gene and the disease.
prostate carcinoma (continued). "One Cdh1+/- mouse at 24 months of age (1/7 Cdh1+/- vs. 0/9 Cdh1+/+, p = 0.44) developed prostate cancer." (PMID 35361739, 2022). "Polymorphic changes among two genes CDH1 (-160C/A) and Exo1 (K589E), have been identified as a crucial parameter for the development of prostate carcinoma, as reported in a study of 100 patients." (PMID 35326902, 2022). "We previously reported down regulation of CDH1 (E- Cadherin) in tumor-adjacent stroma of prostate cancer patients." (PMID 36230846, 2022). "Additionally, 20 CDH1 alterations were identified in patients diagnosed with other primary cancers, namely 10 mutations in breast (mean age at diagnosis 49.6 years old), six in colon (mean age at diagnosis 51.1 years old), two in abdominal carcinomatosis, one in tongue, and one in prostate cancer." (PMID 33809393, 2021). "A recent study in human prostate cancer cells implicated another RBP, hnRNPL, in the post-transcriptional regulation of Cdh1 via modulation of Cdh1 transcript stability." (PMID 35082597, 2021). "KLK3 is also known for its role in EMT induction in prostate cancer cell line PC-3, and has been found to downregulate CDH1 and regulate the cytoskeleton and cell migration process." (PMID 34206049, 2021). "We observed this SLUG+CDH1+ profile in circulating tumour cells (CTCs) obtained from PC3 (a prostate cancer cell line, usually of a more mesenchymal status) (GSE106363)." (PMID 34975907, 2021). "Until now, only a few target genes have been studied in depth to clarify the regulatory network of EZH2 in prostate cancer, including CDH1, DAB2IP, ADRB2." (PMID 31636385, 2020). "In human breast, hepatocellular and prostate cancer hypermethylation of the CDH1 promoter has been observed." (PMID 33076339, 2020). "SIRT1 also prompts cancer cell migration and metastasis in vivo and in vitro by combining with ZEB1 to inhibit CDH1 expression in prostate cancer cells." (PMID 32210140, 2020). "Collectively, these results indicated that there was low expression of CCND1, CDK4 and TWIST1; high expression of SNAI1, SNAI2, and CDH1 was correlated with good prognosis of prostate cancer patients." (PMID 31060254, 2019). "The co-expression of CDH1 and β integrins under combined stimuli is, moreover, in agreement with the recently described cohesive metastatic phenotype in human prostate cancer." (PMID 31426484, 2019). "In prostate cancer, a strong positive correlation was observed between high levels of E-cadherin protein expression and CDH1 transcript levels (Spearman R = 0.9429; P = 0.0167) (Significant regression equation: F = 9.654, P= 0.036, R2 = 0.7071)." (PMID 31850082, 2019). "Meanwhile, DNMT3A has been highlighted as a key repressor of epithelial genes, including CDH1 and GRHL2, in a prostate cancer-associated fibroblast-induced EMT model." (PMID 31372511, 2019). "A subsequent study analyzed CDH1 abnormalities in a large number of prostate cancers, showing that 9% harbor CDH1 deletion and 2% harbor CDH1 mutations." (PMID 31366128, 2019). "Among them, only CDH1 was previously considered to be cancer epigenetic-biomarkers, and reported silenced by hypermethylation in breast, colon, lung, leukemia and prostate cancer." (PMID 28198667, 2017). "Our results show the S-paRNA has a central role in maintaining the silenced state of CDH1 in prostate cancer cell lines: depletion of the S paRNA re-activates E-cadherin expression in CDH1L cancer cells." (PMID 28555645, 2017). "Previous studies showed that SPDEF is required for CDH1 expression in prostate cancer cells and that SPDEF is a downstream target of TGFB1." (PMID 28076331, 2017). "To verify these predictions, we examined the presence of promoter-proximal transcripts in a panel of prostate cancer cell lines with differential CDH1 expression." (PMID 28555645, 2017). "We have previously reported that TFF1 repressed CDH1 expression in prostate carcinoma cells to promote cell invasion." (PMID 25266665, 2014).
prostate carcinoma (continued). "The 5′ CpG island of CDH1 is densely methylated in prostate cancer cell lines (DuPro, TSUPr1, and FNC)." (PMID 22191037, 2011). "EZH2 can regulate CDH1 gene expression to affect EMT process of prostate cancer cell." (PMID 40959108, 2025). "Similarly, research on PDOs from prostate cancer revealed that E-cadherin (CDH1) gene deletions increase sensitivity to DNA damaging agents." (PMID 40476002, 2025). "Furthermore, the KM plotter and GEPIA results demonstrated that when prostate cancer progresses, there are changes in the expression of CDH1, CDH2, VIM, SNAI1, ZEB1, and ZEB2." (PMID 40693059, 2025). "A heatmap analysis reveals that the expression of CDH1 is upregulated in breast, bladder, colon, lung, renal, and thyroid cancer, including prostate cancer, while in adrenal cancer and acute myeloid leukemia (AML), there is no change in the expression of the CDH1 gene." (PMID 40693059, 2025). "Indeed, the potential for prostate cancer invasiveness and metastasis is suppressed by the over-expression of CDH1." (PMID 38675711, 2024). "Overall, among the molecules investigated in this study, the synthesized pigment P7 and its glycosylated analog P3 increase the activities of NFkB, CREB, and SOX transcription factors, leading to the upregulation of CDH1 promoter activity in PC-3 prostate cancer cells." (PMID 38675711, 2024). "Furthermore, the addition of several weak activations or repressions of transcription factors can have a significant biological impact on the regulation of target genes, including CDH1, in prostate cancer cells." (PMID 38675711, 2024). "Since the expression of CDH1 is known to limit the invasion and metastasis of human cancer cells, it would be interesting to assess the influence of synthesized pigments such as 3-DAs and their O-β-D-glucosides on the migration of PC-3 prostate cancer cells." (PMID 38675711, 2024). "Also of interest were several genes associated with prostate cancer metastases including FOXA1, EZH2, SCHLAP1, CDH1, SOX4, SOX9, HOXB13, and TGFBR3." (PMID 38067373, 2023). "In addition to this, lncRNA SNHG1 and RNA binding protein hnRNPL were found to form a complex and coregulate CDH1 to enhance prostate cancer growth and metastasis." (PMID 35846429, 2022). ",69 saRNAs targeting CDH1 were initially discovered in 2006 in the context of prostate cancer." (PMID 36700046, 2022). "Moreover, if one copy of the cadherin 1 (CDH1) gene is lost, this can result in development of diffuse GC, which is also connected with prostate cancer, colorectal cancer, and lobular breast cancer." (PMID 33613500, 2021). "In addition, the MPP8-SIRT1 interaction is considered to play a crucial role in CDH1 repression in prostate cancer cells." (PMID 34395273, 2021). "CDH1 gene (encoding an ATP-dependent chromatin remodeling enzyme) was found to be focally deleted/mutated in 8% prostate cancers, all negative for ETS rearrangements." (PMID 31366128, 2019). "Further studies to evaluate the CDH1 methylation analysis in circulating prostate cancer cells and its prognostic value could be relevant for clinical purposes." (PMID 31850082, 2019). "CDH1 promoter hypermethylation is widely studied in many human cancers, including prostate cancer." (PMID 31850082, 2019). "Therefore we evaluated both DNA methylation (DNAmet) and histone modificationmarks of CDH1 in prostate cancer stem like cells (PCSLCs)." (PMID 30825285, 2019). "Furthermore, we found that the A/A genotype is associated with reduced recurrence-free survival after prostatectomy in prostate cancer patients (P<0.05), consistent with an impact on CDH1 expression during tumour progression." (PMID 28555645, 2017). "The presence of incidental prostate cancer was associated with CNV in miR-15a, CDH1 and ZFHX3." (PMID 28915599, 2017). "In addition, CNV in miR-15a, CDH1 and ZFHX3 were associated with presence of incidental prostate cancer in the RC specimen (all p-values ≤ 0.025)." (PMID 28915599, 2017).
prostate carcinoma (continued). "Furthermore, CNV in miR-15a, CDH1 and ZFHX3 were associated with presence of incidental prostate cancer (p = 0.023, 0.003, 0.025, respectively)." (PMID 28915599, 2017). "CDH1 is found in metastatic breast and prostate cancer cells in bone." (PMID 26011628, 2015). "This heterogeneity of response of various prostate cancer cells to alterations in KLK3 expression may explain why a lower level of CDH1 in CTCs was only observed in one of four models, despite the consistent decrease in KLK3 across all models, in the present study." (PMID 34206049, 2021). "Our findings of CDH1 and CDH3 promoter hypermethylation in NSCLC tumors, with relatively stable methylation for CDH2, are consistent with studies in gastric and prostate cancers." (PMID 40860670, 2025). "In prostate cancer, MAZ promotes bone metastasis through transcriptionally activating the KRas‐dependent RalGEFs pathway, and MAZ binds to the CDH1 promoter to promote epithelial‐mesenchymal transition (EMT)." (PMID 40411278, 2025). "Treatment with β‐sitosterol significantly increases E‐cadherin (CDH1) expression levels in PC‐3 and DU‐145 human prostate cancer cell lines." (PMID 39619995, 2024). "Some hypermethylated genes in prostate cancer are also hypermethylated in other types of cancer, such as p16 in colorectal cancer, gastric cancer, and leukemia; and CDH13, APC, and CDH1 in leukemia." (PMID 37234978, 2023). "β-Sitosterol, a phytosterol that has been proven to be beneficial, inhibits the migration and invasion of human multiple myeloma, pancreatic cancer and prostate cancer by downregulating the expression of VEGF and CDH1." (PMID 38143380, 2023). "(2006) successfully developed saRNAs targeting CDH1, CDKN1A, and VEGF in prostate cancer cell lines." (PMID 36700046, 2022). "SNAI2 regulates E-cadherin (CDH1) gene expression in both human embryonic stem cells and prostate cancer cells to drive migration." (PMID 35905012, 2022). "It was frequently observed that the p16 and CDH1 aberrant promoter methylations can be involved in tumor progression of ESCC, thyroid, oral, breast, gastric, and prostate cancers." (PMID 33883026, 2021). "As demonstrated for prostate cancer, the entry into TGFβ‐mediated EMT initiated by CAFs is dependent on changes in DNA methylation by DNMTA3A, silencing epithelial genes like CDH1 and GRHL2." (PMID 34459003, 2021). "We also examined markers for prostate cancer such as AMACR, EPCAM and C-MYC as well as molecular markers CDH1 and PTEN." (PMID 34911933, 2021). "In prostate cancer cells, SIRT1 and ZEB1 simultaneously bind to CDH1, thereby silencing transcription, which results in metastasis." (PMID 34395273, 2021). "The expression of CDH1 (E-cadherin) was suppressed, while CDH2 (N-cadherin) was highly expressed in metastatic prostate cancer tissues." (PMID 30631151, 2019). "In fact, CDKN2A, ADRB2, CDH1 and SLIT2 were reported to be suppressed by EZH2 in prostate cancer cells and were also targeted by EZH2 in at least one prostate cell line in our ChIP sequencing analysis." (PMID 27835578, 2016). "While the expression of CDH1 was dramatically elevated in the tumor as compared to normal, the GEPIA software was utilized to further validate this, using data from 492 prostate cancer patients and 152 healthy controls." (PMID 40693059, 2025). "In contrast to the strong correlation of antisense transcription from the proximal bidirectional promoter with CDH1 transcription, the distal ncRNA is also found in cells that do not express CDH1 mRNA, such as the prostate cancer cell line PC3." (PMID 38397241, 2024).
prostate carcinoma (continued). "In the realm of breast and prostate cancer research, pioneering observations revealed CDH1 promoter CGI hypermethylation in invasive variants lacking E‐cadherin expression, with subsequent studies validating these findings across diverse tumor types." (PMID 38374872, 2024). "The correlation between CDH1 expression and prostate cancer cell viability is not straightforward and requires further investigation to be fully elucidated." (PMID 38675711, 2024). "Similarly, in NSCLC (non-small cell lung cancer) and prostate cancer, WT1 inhibits Cdh1 and promotes invasion." (PMID 36864480, 2023). "Besides, previous research has demonstrated that several transcription factors, such as FOXM1, MYC, APC/C/CDH1, and E2F, targeted RRM2 in prostate cancer." (PMID 36202136, 2022). "One of the early evidences of the CDH1 CGI hypermethylation was obtained in invasive E-cadherin-negative variants of breast and prostate cancer cell lines and subsequently confirmed in other tumors, including oral and breast cancer." (PMID 32806509, 2020). "The four genes CDH1, MYC, SOS2, and CDKN1A are obtained from the prostate cancer network." (PMID 29670664, 2018). "We found three groups of genes in the EMT differentially expressed list: a) known EMT genes (e.g. CDH1, ZEB1, TGFB, CDH2, VIM, TIMP1), b) EMT genes previously unknown in prostate cancer (LSR, S100A14, DPYSL3) and c) novel EMT genes (including C1orf116)." (PMID 28651527, 2017). "Many studies have suggested that the CDH1 locus (16q) and the CTNNB1 locus (3p) may harbor tumor suppressor genes for prostate cancer and bladder cancer." (PMID 27600761, 2016). "SSX2 knockdown, in the 22Rv1 prostate cancer line, demonstrated a large fold change in many different EMT associated genes (TWIST1, ZEB2, MMP2, VIM, CDH1, CDH2) however these genes did not respond in an anticipated or canonical way." (PMID 27276714, 2016). "Moreover, in prostate cancer, EZH2 can repress the expression of tumor suppressors such as DAB2IP, p16 (CDKN2A), CDK4, E-cadherin (CDH1), MSMB, Ras (KRAS), NF-κB (NFKB1), EMT regulator." (PMID 27835578, 2016). "Several other genes involved in various functions, such as, hormonal response (AR, ESR1, ESR2, RARβ) cell cycle (CCND2, CDKN2A), tumor cell invasion (CAV1,CDH1,CDH13,LAMA3), and signal transduction (DAPK1, DAB2IP, RASSF1) are also affected by DNA hypermethylation in prostate cancer." (PMID 22952798, 2012). "Also, other hypermethylated genes, including CDH1, CDKN2A, CD44, CAV1, HOXD3, and BMP7, have been demonstrated in prostate cancer." (PMID 20671914, 2010). "On the contrary, the combined treatment induced CDH1 expression at both the mRNA and protein levels, and reduced the EMT-related genes, as well as migration by scratch test, thus suggesting that the EMT process is impaired in prostate cancer cells under estrogen plus hypoxia stress." (PMID 31426484, 2019). "However, in the present study the correlations found for CDH1 and RASSF1A in pRCC are the in opposite direction of those described in prostate carcinomas, as higher CDH1 and RASSF1A methylation levels were associated with lower renal tumor stage and grade, respectively." (PMID 17645803, 2007). "For example, in induced pluripotent stem cells (iPSC) and prostate cancer cells, mesenchymal genes, such as ZEB1, ZEB2, CDH2, TWIST and SNAI1/2, are enriched with EZH2 binding, but not epithelial genes such as CDH1 or SNAI3." (PMID 37175580, 2023). "The other DEGs with prognostic significance in prostate cancer that were not differentially expressed in our list of DEGs include IL-7, CCL-2, and CDH1." (PMID 26683658, 2015).
colorectal cancer (463 papers, 1993 to 2026). A primary or metastatic malignant neoplasm that affects the colon or rectum. "Larger studies, including prospective surveillance studies that assess the risk of developing colorectal cancer by performing screening colonoscopies in patients with CDH1 PV are required to confirm our findings." (PMID 40323501, 2025). "E-cadherin, a major actor of cell adhesion in the intestinal barrier, is encoded by the CDH1 gene associated with susceptibility to Crohn Disease (CD) and colorectal cancer." (PMID 38355645, 2024). "CDH1 is also known as E-Cadherin, and its mutation has proven to correlate with tumorigenesis, progression, and invasion of gastric, breast, and colorectal cancers." (PMID 37201027, 2023). "The odds ratio was also increased for CDH1 variants in several other ethnicities for each of breast and colorectal cancer, though in general to a smaller degree, and false discovery rate-corrected q-values were not significant." (PMID 34949788, 2022). "In this review, CDH1 gene was identified as significant prognostic factor for overall survival in colorectal cancer with some studies reporting risk while others protective effect (4 studies)." (PMID 35444210, 2022). "CDH1, which encodes E-cadherin, is a strong candidate for UC susceptibility and is the first genetic correlation between UC and colorectal cancer." (PMID 34360971, 2021). "One study has noted an increased risk of colorectal cancer in a family with a CDH1 missense germline mutation." (PMID 34073553, 2021). "Some studies have also reported cases of colorectal carcinoma associated with loss of E-cadherin function, although its inclusion in CDH1 clinical presentation remains controversial." (PMID 34503169, 2021). "A patient with a pathogenic CDH1 variant (c.1679C > G) had a personal history of microsatellite-stable colorectal cancer at the age of 30 years." (PMID 33322525, 2020). "Further association of CDH1 mutation in patients with colorectal cancer was found and the suppression of CDH1 in pathogenesis of these tumors resulted in an opinion in the cancer society of a syndromic association between these tumors." (PMID 33062523, 2020). "Hereditary diffuse gastric cancer as said earlier has been found to have a close linkage to CDH1 mutation and associated with invasive lobular breast carcinoma, colorectal carcinoma and cleft lip/cleft palate." (PMID 33062523, 2020). "In one study, a CDH1 missense germline mutation co-segregated with colorectal carcinoma; however, the same mutation was also present in the normal population." (PMID 30568591, 2018). "Higher expression of LSD1 and low expression of CDH-1 (E-cadherin) in colorectal cancer were associated with higher tumor-node-metastasis staging and thus poorer prognosis." (PMID 29225781, 2017). "Apparently, there was a confirmed reports that the loss of CDH1 (E-cadherin) expression in colorectal cancer was associated with infiltrative tumor growth pattern and lymph node metastasis." (PMID 27029387, 2016). "Somatic mutations of CDH1 have been identified in sporadic diffuse gastric cancer, colorectal cancer, lobular breast cancer, and ovarian cancer." (PMID 25184143, 2014). "Several studies have documented mutations of CDH1 in cell lines and tissue samples from colorectal carcinoma, albeit rarely." (PMID 23849133, 2013). "In addition, CDH1 is a tumor-suppressor gene involved in the predisposition to several cancers, notably gastric and colorectal cancer." (PMID 38355645, 2024). "Indeed, breast, prostate, and colorectal cancer, as well as some congenital malformations, have also been found to associate with germline CDH1 mutations." (PMID 35277969, 2022). "CDH1 mutations are more predisposed to familial colorectal cancer." (PMID 35154239, 2021).